GPNMB (glycoprotein nmb)
Description:
Could be a melanogenic enzyme.
Synonyms: HGFIN; NMB; PLCA3
Tractability: Antibody: a drug acting on it is in phase 2 or 3 trials; its Gene Ontology location is reachable by antibodies, with high confidence; UniProt places it where antibodies can reach, with medium confidence; UniProt predicts a signal peptide or a membrane-spanning region. PROTAC: ubiquitination databases record sites on it; its protein half-life has been measured. Other modalities: a drug acting on it is in phase 2 or 3 trials.
Gene: Protein-coding gene on chromosome 7 (23,235,967 to 23,275,108, forward strand). Ensembl gene ENSG00000136235.
Subcellular location: Cell membrane; Melanosome membrane; Early endosome membrane
Pathways (Reactome):
Signal Transduction: PTK6 promotes HIF1A stabilization
Gene Ontology:
Molecular function: heparin binding; protein binding; receptor ligand activity; syndecan binding; chemoattractant activity; integrin binding
Biological process: cell-cell signaling; negative regulation of cytokine production; negative regulation of G1/S transition of mitotic cell cycle; negative regulation of T cell activation; negative regulation of T cell proliferation; positive regulation of cell migration; regulation of tissue remodeling; signal transduction; cell adhesion; negative regulation of cell population proliferation; positive chemotaxis; positive regulation of ERK1 and ERK2 cascade; regulation of angiogenesis; negative regulation of tumor necrosis factor production
Cellular component: early endosome membrane; melanosome membrane; membrane; plasma membrane; cytoplasmic vesicle
Genetic constraint (gnomAD): Loss-of-function variants: 52 observed, 43.79 expected, observed/expected ratio (o/e) 1.19, 90% interval 0.95 to 1.5. The upper end of that interval is the gene's LOEUF score, 1.5, which puts it in group 6 of 6, group 1 being the genes least tolerant of losing a copy. Missense variants: 528 observed, 566.58 expected, observed/expected ratio (o/e) 0.93, 90% interval 0.87 to 1. Synonymous variants: 207 observed, 216.54 expected, observed/expected ratio (o/e) 0.96, 90% interval 0.85 to 1.07.
Homologues: Orthologues: chimpanzee GPNMB (96% identical), macaque GPNMB (92% identical), pig GPNMB (76% identical), mouse Gpnmb (72% identical), guinea pig GPNMB (71% identical), rat Gpnmb (71% identical), rabbit GPNMB (64% identical), tropical clawed frog gpnmb (52% identical), zebrafish gpnmb (34% identical). Paralogues in human: PMEL (31% identical), TMEM130 (15% identical).
Diseases named in the same sentence as GPNMB in open-access papers:
GPNMB is named in the same sentence as 207 diseases in open-access papers, as found by Europe PMC text mining. Sharing a sentence is not in itself a finding about the gene and the disease. The quoted sentences say what the papers report.
melanoma (86 papers, 2005 to 2026). A malignant, usually aggressive tumor composed of atypical, neoplastic melanocytes. "Recent evidence also shows that GPNMB is implicated in tumor immune evasion by directly inhibiting T cell activation in melanoma." (PMID 40626360, 2025). "Abnormal expression of GPNMB is not only associated with skin diseases such as dyschromatosis, amyloidosis, and vitiligo, but it can also lead to melanoma." (PMID 41180454, 2025). "It has also been shown that higher circulating GPNMB blood levels of patients with advanced non-small cell lung cancer and malignant melanoma were associated with resistance to immune checkpoint blockade." (PMID 38822058, 2024). "Although GPNMB expression is commonly associated with low metastatic human melanoma cell lines, it has been suggested that genetic variation in GPNMB is linked with PD37." (PMID 37164954, 2023). "The expression level of GPNMB in melanocytes was found to be inversely correlated with the metastatic capacity of human melanomas and was shown to be associated with the development of the retinal pigment epithelium and the iris." (PMID 37627399, 2023). "As GPNMB was originally associated with tumorous cells, GPNMB was widely studied in several types of cancer, such as melanoma, glioma, breast cancer, and gastric cancer." (PMID 34054862, 2021). "GPNMB expression level in melanocytes was reported to be inversely correlated with the metastatic capacity of human melanomas and linked to the developing retinal pigment epithelium and iris." (PMID 22912767, 2012). "In this study, shRNA mediated reduction in GPNMB/OA expression in B16 melanoma cells was shown to cause a reduction in sub-cutaneous tumor growth compared to control cells when injected into syngeneic mice." (PMID 20711474, 2010). "Together, these findings suggest that GPNMB expression marks the quiescent state of melanoma cells and is also associated with their metastatic potential, highlighting GPNMB as a marker to isolate quiescent cells in melanomas, and potential target of the metastatic process in melanoma." (PMID 40528051, 2025). "Furthermore, WNT inhibition resulted in normalization of expression levels of the gene encoding the transmembrane Glycoprotein nmb (Gpnmb), a known marker of melanomas, gliomas and breast cancers, which is also overexpressed in TFE-fusion ccRCCs." (PMID 27668431, 2016). "Senolytic‐resistant SCs released less mitochondrial DNA (mtDNA) and more highly expressed the anti‐inflammatory immune evasion signal, glycoprotein non‐melanoma‐B (GPNMB)." (PMID 41462575, 2026). "Our findings position GPNMB as a valuable marker for isolating quiescent melanoma cells and as a potential therapeutic target to tackle metastasis." (PMID 40528051, 2025). "GPNMB is an endogenous type I transmembrane glycoprotein, first described in melanoma biology, that is elevated in multiple neurodegenerative conditions, including Alzheimer’s disease, amyotrophic lateral sclerosis, and PD." (PMID 41301891, 2025). "GPNMB is a type I transmembrane protein abundantly expressed in melanoma compared to normal tissue and other solid tumors such as glioblastoma and breast cancer where it has been reported as a prognostic factor." (PMID 40528051, 2025). "In melanoma, tumor-derived GPNMB engages Syndecan-4 on T cells to blunt antitumor immunity, with knockout studies demonstrating >50% reduction in B16F10 tumor growth." (PMID 41180454, 2025). "Our findings also demonstrate the potential of targeting GPNMB with GV as a therapeutic strategy to prevent metastatic spread in melanoma patients." (PMID 40528051, 2025). "GPNMB is highly expressed in melanoma, particularly showing co-expression with melanocyte-related genes, and serves as a critical target for the antibody-drug conjugate CR011-vcMMAE." (PMID 41180454, 2025).
melanoma (continued). "Consistent with our observations, GPNMB expression was significantly higher in the KI67- quiescent melanoma cells isolated from metastatic tumors compared to quiescent cells from primary tumors." (PMID 40528051, 2025). "Another LA-TAM marker in blood-circulating monocytes, GPNMB, correlated with melanoma staging and its expression by breast cancer TCs has been described as a prognostic indicator of recurrence." (PMID 40406129, 2025). "Glembatumumab vedotin (CDX-011), targeting glycoprotein NMB (gpNMB), a protein overexpressed in advanced melanoma, has been tested in clinical trials." (PMID 39857682, 2025). "GPNMB, a transmembrane glycoprotein, has been identified for its elevated expression in a melanoma cell line with limited metastatic tendencies." (PMID 40626360, 2025). "Our finding pinpoints GPNMB, a protein uniquely expressed by quiescent cells (QQ and PQ), as a potentially groundbreaking therapeutic target for melanoma." (PMID 40528051, 2025). "Glembatumumab Vedotin (GV), an antibody–drug conjugate (ADC) targeting GPNMB, is being investigated for treating breast and lung cancers, and in advanced melanoma." (PMID 40528051, 2025). "Our research strengthens this possibility by identifying GPNMB as a specific marker for targeting the pro-metastatic and drug resistance phenotypes of quiescent melanoma cells." (PMID 40528051, 2025). "On the other hand, emerging evidence reveals that GPNMB+TAMs in melanoma and breast cancer microenvironments exhibit significant upregulation of immunosuppressive markers including TREM2 and CD206." (PMID 41180454, 2025). "Genetic ablation of GPNMB significantly reduces pulmonary metastatic lesions in B16F10 melanoma models and decreases melanin deposition at metastatic sites." (PMID 41180454, 2025). "GPNMB is widely expressed in several cells and tissues under normal conditions, and significantly elevated in several malignant tissues including glioma, melanoma, breast cancer cells, etc." (PMID 39263169, 2024). "Further, we detected signature melanosomal markers TYR, DCT, GPR143, and GPNMB in the melanosomes derived from melanoma cells, fibroblasts and keratinocytes (Fig. EV2I)." (PMID 38719996, 2024). "In melanoma cells, GPNMB attenuates the activation of T cells that are activated via syndecan-4, allowing the evasion of melanoma cells from immunological recognition and destruction." (PMID 38822058, 2024). "Several reports have shown that patients suffering types of cancer display highly expanded GPNMB+ MDSCs in the blood, such as melanoma, lung, colorectal, kidney, pancreatic, breast, bladder, or prostate cancer." (PMID 38140790, 2023). "GPNMB, also known as osteoactivin, is a type 1 transmembrane glycoprotein that was originally identified in low-metastatic melanoma cell lines in 1995." (PMID 37510803, 2023). "GPNMB+CD11b+Gr1+ cells were massively expanded in melanoma‐bearing animals, and showed prominent suppressive effects on T cell activation both in vivo and in vitro." (PMID 38140790, 2023). "These CD14+HLA−DRno/low cells isolated from melanoma patients significantly reduced the IFN‐γ secretion of T cell in the cocultures of GPNMB+ MDSCs and autologous activated T cells." (PMID 38140790, 2023). "GPNMB is a highly glycosylated type 1 transmembrane protein that was first described in 1995 in melanoma cell lines." (PMID 38140790, 2023). "The prognosis of these cancers is poor when overexpressed, and GPNMB promotes invasion and metastasis in malignant melanoma." (PMID 36061142, 2022). "With respect to metastasis, melanoma uses the GPNMB pathway to increase metastatic success by secreting soluble GPNMB, which binds to the vascular niche of DHL + endothelial cells." (PMID 36061142, 2022). "GPNMB is a transmembrane glycoprotein that is highly expressed in a melanoma cell line and has low metastatic properties." (PMID 36224652, 2022).
melanoma (continued). "To analyze the cellular localization of GPNMB, we conducted immunostaining for GPNMB in a melanoma cell line that expresses high levels of GPNMB." (PMID 35444208, 2022). "Fluorescent imaging revealed that GPNMB was co-localized with Lysotracker, suggesting a role in the lysosomes, which was similar to that in the melanoma cell line." (PMID 35444208, 2022). "GPNMB is an endogenous type 1 transmembrane glycoprotein that was first described in 1995 as more highly expressed in low-metastatic melanoma cell lines." (PMID 34054862, 2021). "The authors further overexpressed the glycoprotein non-melanoma clone B (GPNMB), which facilitated osteoblast differentiation, in the BMSCs and released the EVs with high GPNMB expression (GPNMB-EVs)." (PMID 34884554, 2021). "GPNMB, the most highly expressed gene in primary module 2 of melanoma, locates to the surface of melanoma cells." (PMID 34570764, 2021). "GPNMB (also designated as osteoactivin) is a type I transmembrane protein originally discovered in a melanoma cell line." (PMID 33947460, 2021). "GPNMB was found to be expressed in primary melanocytes, melanoma cell lines, and keratinocytes that contained PSVK1—i.e., human primary epidermal keratinocytes from adults and newborns." (PMID 34639184, 2021). "Combination therapy, however, which includes a BRAF or MEK inhibitor, combined with glembatumumab vedotin (an antibody drug conjugate that targets GPNMB) inhibits GPNMB and effectively controls the growth of Melanoma." (PMID 34570764, 2021). "Tomihari confirmed that GPNMB in patients with melanoma has the ability to downregulate the activation of melanoma-reactive T cells, thereby allowing melanoma to evade immunologic recognition and destruction." (PMID 32833670, 2020). "We then proved, through observation, that the expression of GPNMB in NHEKs using the validated and specific anti-GPNMB antibody was the same as that of melanoma cells and NHEMs." (PMID 32188902, 2020). "Some reports have suggested that GPNMB might be involved in the differentiation of tissue cells and metastasis of tumor cells, and is associated with the occurrence and invasion of melanoma cells, glioma cells, breast, colorectal cancer, and prostate cancer cells." (PMID 32833670, 2020). "The GPNMB antibody which was proved specific in melanoma and melanocyte cells (as positive controls) was used for detecting WB band and immunostaining signal in NHEKs." (PMID 32188902, 2020). "GPNMB was originally discovered in a melanoma cell line and occurs in various tissues and cell types." (PMID 30586924, 2018). "Overexpression of GPNMB has been correlated with tumor formation and metastasis in melanomas, gliomas, hepatocellular carcinoma, and breast cancer." (PMID 29552294, 2018). "Glycoprotein nonmetastatic melanoma protein B (GPNMB), also known as osteoactivin, dendritic cell-heparin integrin ligand, and hematopoietic growth factor-inducible neurokinin-1 type, was initially cloned from poorly metastatic melanoma cells." (PMID 28939899, 2017). "Preclinical studies in melanoma have shown that the level of gpNMB expression is proportional to the effectiveness of gpNMB-targeted therapy via an ADC called glembatumumab vedotin (CDX-011)." (PMID 29262642, 2017). "The next candidate protein that has been reported to be upregulated in various cancer types (e.g., melanoma, glioma and breast cancer) is GPNMB." (PMID 29299134, 2017). "As a control, we used the SK-Mel2 human melanoma cells, as this cell line highly expresses gpNMB (6.8 ± 0.3)." (PMID 29262642, 2017). "Several recent studies have identified high GPNMB expression in malignancies, including in aggressive melanoma, glioblastoma multiforme, hepatocellular carcinoma, and triple negative breast cancers." (PMID 27078017, 2016).
melanoma (continued). "GPNMB has been shown to be increased in multiple malignancies, including breast cancer, prostate cancer, glioblastoma multiforme, melanoma, gastric cancer, colorectal carcinoma, small cell lung cancer, renal cell carcinoma, and hepatocellular carcinoma." (PMID 27078017, 2016). "Glembatumumab vedotin showed in vitro cytotoxicity that was related to GPNMB expression, and it induced complete regressions in GPNMB-expressing melanoma and breast cancer xenografts." (PMID 26380223, 2015). "Emerging expression analyses using clinical samples also suggest GPNMB as a potential oncogene in several cancers, including melanoma, glioma, breast, and GC 14–19." (PMID 26077887, 2015). "Many of these genes have previously been implicated in melanoma metastasis and prognosis prediction, including MYC, GPNMB, GAB2, and SATB1." (PMID 25116415, 2014). "GPNMB, a highly glycosylated type I transmembrane protein, was initially cloned from low-metastatic melanoma cells in 1995." (PMID 22912767, 2012). "GPNMB/OA is localized to diverse subcellular locations within the cell, including the plasma membrane of cancer cells, within melanosomes of melanoma cells and within endocytic/lysosomal vesicles in osteoclasts." (PMID 20711474, 2010). "GPNMB was first cloned from a melanoma cell line and is expressed at high level in many melanoma cell lines." (PMID 21209915, 2010). "The mechanism by which GPNMB/OA promoted melanoma tumor outgrowth was through suppression of T-cell activation, which normally serves to limit tumor outgrowth." (PMID 20711474, 2010). "Recently, it has been shown that GPNMB/OA expressed in melanoma cells promotes their growth by impairing the activation of melanoma-reactive T-cells." (PMID 20711474, 2010). "Recently, an alternate mechanism, involving GPNMB/OA-mediated suppression of T-cell activation, has been proposed to explain how GPNMB/OA can promote the growth of melanoma tumors." (PMID 20711474, 2010). "Since MiTF is often amplified in melanoma, GPNMB expression in melanoma cells is likely to be a result of elevated MiTF transcriptional activity." (PMID 21209915, 2010). "As in a previous report, we found high GPNMB expression in an MiTF-positive melanoma cell line, SK-MEL-28." (PMID 21209915, 2010). "These fragments are products of post-translational proteolytic processing and have previously been described in C2C12 myoblast cells engineered to overexpress GPNMB/OA, as well as in melanocytes and melanoma cells endogenously expressing GPNMB/OA." (PMID 20711474, 2010). "In melanoma metastasis, there is an inverse relationship between the expression of GPNMB and calcyclin or thymosin-beta-10, two other potential markers for the progression of cutaneous melanoma." (PMID 19750230, 2009). "Equally, glycoprotein NMB (GPNMB) is a type I membrane protein with homology to the melanoma antigen pMEL17." (PMID 19146682, 2009). "Two-thirds of highly metastatic melanomas expressing recombinant GPNMB showed slower subcutaneous tumor growth, whereas one-third showed reduced potential for spontaneous metastasis in nude mice or iris pigment dispersion in DBA/2J mice." (PMID 19750230, 2009). "In melanoma, ADCs targeting TAAs like gpNMB and c-Met have shown promising results." (PMID 39857682, 2025). "Consequently, GPNMB has emerged as a potential therapeutic target for multiple cancers, including melanoma, breast cancer, and osteosarcoma." (PMID 41180454, 2025). "GPNMB originally identified in melanoma in 1995, has been recognized as a pleiotropic regulator modulating both physiological homeostasis and disease pathogenesis through its multidomain structure containing an RGD integrin-binding motif, PKD domain, and hemITAM signaling motif." (PMID 41180454, 2025). "GPNMB, a marker for cancer stem cells in many cancers, presents a paradox in melanoma." (PMID 40528051, 2025).